APOE (apolipoprotein E)
Description:
APOE is an apolipoprotein, a protein associating with lipid particles, that mainly functions in lipoprotein-mediated lipid transport between organs via the plasma and interstitial fluids. APOE is a core component of plasma lipoproteins and is involved in their production, conversion and clearance. Apolipoproteins are amphipathic molecules that interact both with lipids of the lipoprotein particle core and the aqueous environment of the plasma. As such, APOE associates with chylomicrons, chylomicron remnants, very low density lipoproteins (VLDL) and intermediate density lipoproteins (IDL) but shows a preferential binding to high-density lipoproteins (HDL). Finally, APOE also has a heparin-binding activity and binds heparan-sulfate proteoglycans on the surface of cells, a property that supports the capture and the receptor-mediated uptake of APOE-containing lipoproteins by cells. A main function of APOE is to mediate lipoprotein clearance through the uptake of chylomicrons, VLDLs, and HDLs by hepatocytes. APOE is also involved in the biosynthesis by the liver of VLDLs as well as their uptake by peripheral tissues ensuring the delivery of triglycerides and energy storage in muscle, heart and adipose tissues. By participating in the lipoprotein-mediated distribution of lipids among tissues, APOE plays a critical role in plasma and tissues lipid homeostasis. APOE is also involved in two steps of reverse cholesterol transport, the HDLs-mediated transport of cholesterol from peripheral tissues to the liver, and thereby plays an important role in cholesterol homeostasis. First, it is functionally associated with ABCA1 in the biogenesis of HDLs in tissues. Second, it is enriched in circulating HDLs and mediates their uptake by hepatocytes. APOE also plays an important role in lipid transport in the central nervous system, regulating neuron survival and sprouting. APOE is also involved in innate and adaptive immune responses, controlling for instance the survival of myeloid-derived suppressor cells (By similarity). Binds to the immune cell receptor LILRB4. APOE may also play a role in transcription regulation through a receptor-dependent and cholesterol-independent mechanism, that activates MAP3K12 and a non-canonical MAPK signal transduction pathway that results in enhanced AP-1-mediated transcription of APP. This interaction is probably promoted via the up-regulation of cellular autophagy by the virus.
Synonyms: Apo-E; AD2; ApoE4; LDLCQ5; LPG
Tractability: Small molecule: a structure with a bound ligand is known. Antibody: UniProt places it where antibodies can reach, with high confidence; its Gene Ontology location is reachable by antibodies, with high confidence; UniProt predicts a signal peptide or a membrane-spanning region. PROTAC: ubiquitination databases record sites on it; its protein half-life has been measured.
Safety:
Unwanted effects reported when the protein is acted on. In parentheses: how it was acted on, where the effect was seen, and who reports it.
elevated plasma lipids (source: ClinPGx)
elevated triglycerides (source: ClinPGx)
hemorrhage (source: ClinPGx)
hypertriglyceridemia (source: ClinPGx)
Gene: Protein-coding gene on chromosome 19 (44,903,787 to 44,909,396, forward strand). Ensembl gene ENSG00000130203.
Subcellular location: Secreted; Secreted, extracellular space; Secreted, extracellular space, extracellular matrix; Extracellular vesicle; Endosome, multivesicular body
Subcellular location (Human Protein Atlas): Vesicles; Predicted to be secreted
Pathways (Reactome):
Transport of small molecules: Chylomicron assembly; Chylomicron clearance; Chylomicron remodeling; HDL remodeling
Metabolism of proteins: Amyloid fiber formation; Post-translational protein phosphorylation; Regulation of Insulin-like Growth Factor (IGF) transport and uptake by Insulin-like Growth Factor Binding Proteins (IGFBPs)
Signal Transduction: NR1H3 & NR1H2 regulate gene expression linked to cholesterol transport and efflux; Nuclear signaling by ERBB4
Gene expression (Transcription): Transcriptional regulation by the AP-2 (TFAP2) family of transcription factors
Sensory Perception: Retinoid metabolism and transport
Vesicle-mediated transport: Scavenging by Class A Receptors
Gene Ontology:
Molecular function: amyloid-beta binding; antioxidant activity; enzyme binding; heparan sulfate proteoglycan binding; heparin binding; identical protein binding; lipid binding; lipid transporter activity; low-density lipoprotein particle receptor binding; metal chelating activity; phosphatidylcholine-sterol O-acyltransferase activator activity; phospholipid binding; protein binding; protein dimerization activity; protein homodimerization activity; protein-containing complex binding; receptor ligand activity; signaling receptor binding; tau protein binding; very-low-density lipoprotein particle receptor binding; cholesterol transfer activity; structural molecule activity; lipoprotein particle binding
Biological process: AMPA glutamate receptor clustering; amyloid precursor protein metabolic process; cellular response to lipoprotein particle stimulus; cholesterol efflux; cholesterol homeostasis; cholesterol metabolic process; chylomicron remnant clearance; fatty acid homeostasis; G protein-coupled receptor signaling pathway; high-density lipoprotein particle assembly; high-density lipoprotein particle clearance; high-density lipoprotein particle remodeling; host-mediated activation of viral process; intermediate-density lipoprotein particle clearance; lipoprotein biosynthetic process; locomotory exploration behavior; long-chain fatty acid transport; long-term memory; melanosome organization; negative regulation of amyloid-beta formation; negative regulation of blood coagulation; negative regulation of blood vessel endothelial cell migration; negative regulation of canonical Wnt signaling pathway; negative regulation of cholesterol biosynthetic process; negative regulation of endothelial cell migration; and 69 more
Cellular component: blood microparticle; chylomicron; chylomicron remnant; endoplasmic reticulum; extracellular exosome; extracellular matrix; extracellular region; extracellular vesicle; glutamatergic synapse; Golgi apparatus; high-density lipoprotein particle; intermediate-density lipoprotein particle; lipoprotein particle; low-density lipoprotein particle; melanosome; membrane; multivesicular body, internal vesicle; nucleus; synaptic cleft; very-low-density lipoprotein particle; clathrin-coated endocytic vesicle membrane; cytoplasm; dendrite; discoidal high-density lipoprotein particle; early endosome; and 5 more
Genetic constraint (gnomAD): Loss-of-function variants: 12 observed, 14.73 expected, observed/expected ratio (o/e) 0.81, 90% interval 0.52 to 1.32. The upper end of that interval is the gene's LOEUF score, 1.32, which puts it in group 5 of 6, group 1 being the genes least tolerant of losing a copy. Missense variants: 471 observed, 408.34 expected, observed/expected ratio (o/e) 1.15, 90% interval 1.07 to 1.25. Synonymous variants: 211 observed, 184.67 expected, observed/expected ratio (o/e) 1.14, 90% interval 1.02 to 1.28.
Homologues: Orthologues: chimpanzee APOE (97% identical), macaque APOE (94% identical), pig APOE (72% identical), mouse Apoe (71% identical), rat Apoe (70% identical), dog APOE (69% identical), guinea pig APOE (69% identical), zebrafish apoeb (25% identical), tropical clawed frog apoe (23% identical), zebrafish apoea (22% identical). Paralogues in human: APOA4 (19% identical), APOA1 (17% identical), APOA5 (15% identical).
Diseases named in the same sentence as APOE in open-access papers:
APOE is named in the same sentence as 840 diseases in open-access papers, as found by Europe PMC text mining. Sharing a sentence is not in itself a finding about the gene and the disease. The quoted sentences say what the papers report.
atherosclerosis (4,004 papers, 2001 to 2026). A disease characterized by the build-up of fatty material and calcium deposition in the arterial wall resulting in partial or complete occlusion of the arterial lumen. "ApoE-/- C57 mice were injected recombinant adeno-associated virus serotype 9 through tail vein to explore the role of PIM1 in atherosclerosis." (PMID 39744686, 2025). "Researchers have shown that eplerenone reduces oxidative stress and inflammation and reduces the subsequent atherosclerosis lesions in apoE-deficient mice fed a high-cholesterol diet." (PMID 39859256, 2025). "This study aimed to clarify the inhibitory role of O3-RI on atherosclerosis, specifically focusing on its association with the regulation of gut microbiota and metabolites in ApoE−/− mice." (PMID 40636499, 2025). "To this end, we assessed the in vivo role of platelet Jak2 in atherosclerosis using ApoE−/− mice with platelet Jak2 deficiency." (PMID 40825505, 2025). "Here, we showed that capsiate treatment alleviates atherosclerosis in atherosclerosis-prone apolipoprotein E-deficient (ApoE−/−) mice." (PMID 40029381, 2025). "Substantial evidence has long established the association between APOE and coronary artery disease as well as the severe hyperlipidemia and atherosclerosis observed in ApoE−/− mice." (PMID 40649979, 2025). "Exposure studies using a PXR-humanized mouse model demonstrated that BPA increased atherosclerosis in atherosclerosis-prone ApoE-deficient mice in a human PXR-dependent manner." (PMID 40857741, 2025). "Circ‐PIAS1‐5 is identified as a potential diagnostic biomarker of HHcy‐associated atherosclerosis in male “apolipoprotein E knockout (ApoE−/−)” mice." (PMID 40089857, 2025). "In ApoE-deficient mice (ApoE−/−), Plin2 promoted foam cell formation and its inactivation led to less formation of LDs and protection from atherosclerosis." (PMID 39859272, 2025). "MeHg intoxication worsens cardiovascular risk, aggravating atherosclerosis in wild-type and APOE ko mice." (PMID 40406630, 2025). "Recent research has demonstrated that the transplantation of MSCs can decrease atherosclerosis in ApoE-deficient mice that were fed a high-fat diet." (PMID 39866781, 2025). "While APOE ε4 is associated with higher cardiovascular risk, exacerbating atherosclerosis and arterial calcification, APOE ε2’s role is more complex." (PMID 40149595, 2025). "Apolipoprotein-E (ApoE) has been implicated in several diseases, including AD and cardiovascular disease such as atherosclerosis." (PMID 40678242, 2025). "This study explores the anti-atherosclerosis effects of DHL on apolipoprotein E-deficient (ApoE−/−) mice, and the potential mechanism on macrophage-derived foam cells." (PMID 40537740, 2025). "ApoE is primarily known for its role in lipid metabolism and atherosclerosis susceptibility, but it also exerts significant effects on the vascular endothelium." (PMID 41465167, 2025). "A recent study reported that CNP administration via osmotic pumps or CNP overexpression attenuated atherosclerosis and increased plaque stability in ApoE-deficient mice." (PMID 39814746, 2025). "A dietary supplementation study was carried out with atherosclerosis-prone apolipoprotein E deficient (ApoE−/−) mice to determine the effects of increased circulating glycine levels on cardiometabolic traits and aortic lesion formation." (PMID 39796632, 2025). "Another study investigates the increased apoptosis in spiral ganglion neurons in apolipoprotein E-knockout mice under the influence of a Western diet, highlighting a link between dietary factors, atherosclerosis, and hearing loss." (PMID 40001646, 2025). "Conversely, the APOE ε2 allele is associated with a lower risk of cardiovascular disease and subclinical atherosclerosis, although this protective effect appears largely independent of LDL-cholesterol levels." (PMID 40275327, 2025).
atherosclerosis (continued). "Deletion of the ANGPTL3 gene in ApoE-deficient mice has been reported to reduce the development of atherosclerosis." (PMID 40503438, 2025). "A mouse model of HIV-associated atherosclerosis (Tg26+/-ApoE-/-) exhibited increased plaque area compared with the ApoE-/- mouse, linked to elevated indoleamine 2,3-dioxygenase (IDO) activity." (PMID 40853965, 2025). "Evidence from transgenic and knockout mouse models has highlighted the isoform-specific effects of ApoE, showing how deficiency accelerates atherosclerosis and how human-like isoform knock-in reproduces distinct lipid and vascular phenotypes." (PMID 41465167, 2025). "Vascular dysfunction and atherosclerosis occur early in ApoE-deficient mice, leading to decreased cerebral blood flow and impaired autonomic control of the cerebral vasculature." (PMID 40026711, 2025). "Overexpression of NFIA decreased the circulation of inflammatory cytokines, including IL‐6 and TNF‐α, and promoted regression of atherosclerosis in apolipoprotein E‐deficient mice, possibly through the nuclear factor kappa B (NF‐κB) pathway." (PMID 40560736, 2025). "Intriguingly, all three triggers accelerate atherosclerosis in apolipoprotein E‐knockout mice, suggesting shared pathogenic and pathophysiological mechanisms between KD vasculitis and atherosclerosis." (PMID 41017238, 2025). "In vivo, apolipoprotein E‐deficient (ApoE‐/‐) mice, an established model for atherosclerosis research, were fed a high‐fat diet (HFD) and divided into two experimental groups." (PMID 40285666, 2025). "In a recent preclinical study on cholesterol-fed apolipoprotein E-deficient mice, long-term S1P elevation produced accelerated atherosclerosis and decreased plaque stability resulting in plaque rupture and atherothrombosis." (PMID 41268158, 2025). "One study investigated the influence of aldosterone on atherosclerosis in mice with apolipoprotein E (Apo-E) deficiency." (PMID 39859256, 2025). "Daily administration of IL-12 to apoE-deficient mice resulted in the development of atherosclerosis." (PMID 40823653, 2025). "All mice for these experiments were bred on an ApoE-deficient background and fed an atherogenic diet for 18 weeks before atherosclerosis was analyzed." (PMID 39814746, 2025). "Sitagliptin was reported to improve endothelial and monocyte function and decrease atherosclerosis lesions in mice with a deficiency in apolipoprotein E." (PMID 40136627, 2025). "In this study, apolipoprotein E-deficient (ApoE−/−) mice served as an atherosclerosis model, while human umbilical vascular endothelial cells (HUVECs) were used as cellular models." (PMID 40186131, 2025). "For example, in an ApoE-/-/polG-/- murine model, atherosclerosis progression was associated with defects of ETC function without an increase in electron leakage from ETC." (PMID 39940788, 2025). "Hypercholesterolemia induced neutrophilia and neutrophil accumulation in an early stage of atherosclerosis in apolipoprotein E (Apo E)-deficient mice." (PMID 40305368, 2025). "A study conducted to compare the effects of atherosclerosis on ApoE deficient mice vs. healthy mice has shown that the presence of Th22 and IL-22 was directly associated with the level of inflammation." (PMID 39944697, 2025). "Loss of PPARγ function in the vascular endothelium enhances atherosclerosis in high-fat diet-fed apoE-/- mice." (PMID 40440080, 2025).